CD47 (CD47 molecule)
Diseases named in the same sentence as CD47 in open-access papers (continued):
Sharing a sentence is not in itself a finding about the gene and the disease.
tumor (continued). "Overexpression of CD47, therefore, seems to protect tumor cells from innate immune attack, in addition to potential downstream adaptive mechanisms that may be involved in the priming of a T cell response." (PMID 25941795, 2015). "In our in vivo study, down-regulation of expression of CD47 in tumor cells by blockade PD-1 may improve phagocytosis of macrophage to enhance antitumor immunity." (PMID 26573233, 2015). "TSP-1 was indeed reported to be over-expressed in tumor stroma, and its contribution through CD47 ligation remains controversial in this context due to the pleiotropic nature of TSP-1 and its ability to induce opposite effects in different host organ environments." (PMID 26046793, 2015). "Blockade of CD47/SIRPα axis led to efficient and rapid phagocytosis of multiple tumor cell types." (PMID 26573233, 2015). "In addition, activation of macrophage anti-tumor activity has been also an area of active investigation, in particular regarding the blockade of the binding between CD47 molecules and macrophage signal regulatory protein-alpha (SIRPα)." (PMID 26093091, 2015). "Thus, CD47 is associated with tumor progression, metastasis, and outcome, which suggests the CSC-based therapeutic potential of targeting CD47 in cancer 7,20,21,24–26." (PMID 26077800, 2015). "TSP-1 is overexpressed in tumor stroma and could sustain cancer cell invasion by increasing ECM-associated proteolytic activity through CD47 ligation." (PMID 26046793, 2015). "Tumors may also escape from tumor surveillance utilizing the interaction between monocytic CD47 and SIRP-α, which is an inhibitory receptor of phagocytosis." (PMID 24600454, 2014). "CD47 has also been shown to be involved in the regulation of intracellular Ca2+ ([Ca2+]i), exemplified by its regulation of an integrin-dependent increase in [Ca2+]i in endothelial cells and tumor cells, and that CD47 synergizes with T cell receptor-stimulated elevations of [Ca2+]i in T lymphocytes." (PMID 23401787, 2013). "Among the upregulated genes, we identified several oncogenes (Ets2, Fyn, Fos, Rab30 and Src), various tumor markers (Cyp1b1, Gpa33, Cd47, Fam129a, st7l, chka, Lgalsbp, Antxr1 and Ly6a) and other genes related to tumor promotion (Cxcl10, Trim25, Grn, Foxc2, Bmp7 and Irs1)." (PMID 23936067, 2013). "In addition, tumour cells often overexpress CD47, which — via interaction with signal-regulatory protein-alpha (SIRPα) — inhibits elimination of tumour cells by macrophages." (PMID 23918228, 2013). "In addition, blocking antibodies directed against CD47 promoted phagocytosis as suggested through disruption of CD47-SIRPα interaction and this enhanced tumor clearance in vivo." (PMID 23320069, 2013). "CD47 (also called integrin-associated protein, IAP) is a cell surface transmembrane glycoprotein that is widely expressed on many cells of epithelial and mesenchymal origin, including hMSC, and is highly expressed on tumor cells, such as leukemia." (PMID 24073274, 2013). "Similarly, tumor-derived lactoferrin and CD47, which have been shown to interact with signal regulatory protein-α on phagocytes, will bind DCs and release inhibitory signals that will prevent phagocytosis." (PMID 23606870, 2013). "Therefore, we assessed CD47 expression not only tumor cells (TPS) but also combined with immune cells (CPS) in current study (TPS and CPS commonly utilized in the evaluation of immunotherapy biomarkers, including in PD-1/PD-L1 inhibitor studies approved in Japan)." (PMID 40926176, 2026). "Finally, we verify that DNAJC13-knockout decrease tumor burden when treated with CD47 blockade." (PMID 41601654, 2026). "Moreover, PA NPs functionalized with anti-CD47 antibodies selectively bound to tumor cells, blocked the CD47-SIRPα "don't eat me" signal, and actively reprogrammed macrophages to enhance phagocytic clearance of tumor cells." (PMID 42089417, 2026).
tumor (continued). "Interestingly, despite the well-established role of CD47 in suppressing innate immune clearance, we did not observe significant tumor growth delay in mice bearing CD47- or DNAJC13-deficient tumors in the absence of therapeutic intervention." (PMID 41601654, 2026). "By combining the CD47 blockade with a tumor-specific antigen (e.g., CD47 × DLL3, CD47 × HER2, or CD47 × CLDN 18.2), it may be possible to selectively restore macrophage-driven tumor clearance while minimizing systemic toxicity associated with global CD47 inhibition." (PMID 40508202, 2025). "In this study, we characterized the expression of TAAs on PDAC cell lines and patient tumor samples and tested the efficacy of IgA mAbs directed against these TAAs, to investigate whether IgA mAbs in combination with CD47 blockade could pose a promising therapeutic strategy for PDAC." (PMID 40358156, 2025). "Moreover, combining IDCs with targeted therapies—such as AXL, VEGF, or CD47 inhibitors—could help to remodel the tumor microenvironment, reduce stromal barriers, and improve intratumoral drug penetration." (PMID 40603576, 2025). "Likewise, vaccination with CD47-knockdown tumor cells produced similar effects." (PMID 41380903, 2025). "Consequently, enhancing the sensitivity of chemotherapy by inhibiting the uptake of LAT2-mediated amino acids to reduce CD47 and by enhancing the infiltration and phagocytosis of tumour cells by macrophages has emerged as a potential strategy for the treatment of cancer." (PMID 40598593, 2025). "Notably, CD47 plays an important role in tumor escape from macrophage-mediated phagocytosis." (PMID 40296909, 2025). "This specificity for tumors may be attributed to the expression of “eat-me” signals such as calreticulin, which can trigger phagocytosis by macrophages, leading tumor cells to be more reliant on expression of “Don’t eat me” signals such as CD47 to avoid being killed compared to healthy cells." (PMID 40078999, 2025). "This suggests that CD47 inhibition therapy-enhanced efferocytosis may promote cancer immunosuppression by expanding Tregs and enhancing PD-1 expression on T cells, thereby weakening anti-tumor effects." (PMID 40821806, 2025). "Therefore, TRAF2/CD47 pathway regulated tumor innate immune response." (PMID 39665172, 2025). "Furthermore, CD47 inhibition may enhance the anti-tumor activity of cisplatin against NSCLC cells and further augments macrophage-mediated phagocytosis." (PMID 40507214, 2025). "Furthermore, the tumor cells dampen antitumor response by engaging in the CD47-SIRPα interaction." (PMID 41176596, 2025). "Blocking CD47 combined with radiotherapy has radioprotection effects in normal tissues and organs, which contribute to normal cell survival involving various tissues (muscle, skin, vascular, endothelial tissue) and bone marrow, whereas it increases tumor cells sensitivity to radiotherapy." (PMID 40835598, 2025). "Moreover, these vectorized CD47 blocking agents are localized within the tumor microenvironment." (PMID 41322194, 2025). "Moreover, CD47 could induce compartmental remodeling of tumor-infiltrating immune cells within the pancreatic cancer microenvironment." (PMID 40861801, 2025). "Additionally, the anti-tumor activity of CDH17-CAR-NK cells is synergistically enhanced by CD47–signal regulatory protein α (SIRPα) axis inhibitor CV1, likely through augmented macrophages activation and an increase in M1-phenotype macrophages in the tumor microenvironment." (PMID 40487639, 2025). "Therefore, we first examined whether the Vpr peptide affects the expression of CD47 on the tumor cell surface to explore the feasibility of combining the Vpr peptide in situ vaccine with CD47 blockade therapy." (PMID 40733687, 2025). "Moreover, this nanovaccine can alleviate chemotherapy‐induced immunosuppression by augmenting the proportion of M1‐like TAMs, enhancing the infiltration of CD8+ T cells, and downregulating the expression of CD47 through the reduction of HIF1A in ID8 tumor cells." (PMID 39985265, 2025).
tumor (continued). "Additionally, the CD47/SIRPα axis is being actively explored for its role in various cancers, especially hematological malignancies, to restore macrophage-mediated phagocytosis of tumor cells." (PMID 41233805, 2025). "ZBP1 may also stimulate radiation-induced tumor cell phagocytosis, as a recent study has shown that inhibiting the phagocytosis inhibitor CD47 resulted in expansion of APCs and effector T cell responses in distant, non-irradiated tumors to potentiate abscopal responses." (PMID 41282221, 2025). "Research showed that tumor cells may resist macrophage phagocytosis even after CD47 inhibition." (PMID 40422244, 2025). "An important example of bioinspired design is the fusion of CD47-expressing tumour-derived exosomes with cRGD-modified liposomes co-loaded with miR-497 and triptolide (TP), producing hybrid nanoparticles (miR497/TP-HENPs) that markedly enhanced tumour accumulation and induced apoptosis." (PMID 41181109, 2025). "Thus, inhibiting CD47 on tumor cells and activating the TLR signaling pathway in macrophages may enhance PrCR." (PMID 40422244, 2025). "Consequently, anti-CD47 treatments may reduce fusion rates and tumour immune evasion, presenting a novel therapeutic avenue." (PMID 39967663, 2025). "Therefore, oAd-SA treatment may elicit a stronger tumor-targeting immune response as compared to anti-CD47/SIRPα antibodies alone or control virus." (PMID 40070841, 2025). "Notably, these findings indicate that the nanovaccine can also mitigate chemotherapy‐induced immunosuppression by increasing the proportion of M1‐like TAMs and reducing the expression of CD47 on tumor cells, thereby achieving a synergistic effect in tumor immunotherapy." (PMID 39985265, 2025). "Additionally, systemic tumour-antigen-specific immune responses are stimulated by a nanobody antagonist of CD47 (CD47nb)-expressing bacteria, which inhibits the growth of untreated tumours and provides evidence of the abscopal effect of engineered bacterial immunotherapy." (PMID 40792261, 2025). "To determine whether SMYD3 drives tumor immune evasion via CD47 upregulation and subsequent activation of SREBP1 expression, we overexpressed SREBP1 in stable SMYD3‐knockdown 786‐O and TK10 cells to investigate whether the effects of SMYD3 knockdown could be eliminated upon SREBP1 overexpression." (PMID 40548645, 2025). "Further studies with larger sample sizes are necessary to better define the real prognostic value of CD47 overexpression in the complexity of AML tumor microenvironment and, possibly, to identify a subgroup of patients who could derive maximum benefit from emerging CD47-SIRPα blocking therapies." (PMID 40369208, 2025). "We further show that the potency of the engineered long-acting human IgA against tumor cells with intermediate target antigen expression levels could be enhanced by myeloid checkpoint inhibitors targeting the signal regulatory protein α-CD47 axis." (PMID 40041621, 2025). "The CD47 protein, frequently overexpressed on malignant cell surfaces, engages with signal regulatory protein alpha (SIRPα) expressed by myeloid cells (particularly macrophages) to transmit an immunosuppressive “don't eat me” signal, enabling tumor immune evasion through phagocytosis inhibition." (PMID 40892295, 2025). "CD47 blockade is hypothesized to trigger tumor cell phagocytosis by TAMs." (PMID 41415295, 2025). "Therefore, the association between the reported CD47 expression and adverse pathological features (including advanced TNM stage, lymphovascular invasion and tumor budding) should be interpreted with caution, as the current evidence only indicates a correlation rather than a causal relationship." (PMID 41514569, 2025). "Furthermore, induction of autophagy significantly enhanced CD47 antibody anti‐tumor immunotherapy." (PMID 39665172, 2025).
tumor (continued). "CD47 is a well-characterized immune evasion molecule in tumor biology, and its overexpression in therapeutic cells raises concerns about off-target effects, including interference with dendritic-cell-mediated antigen presentation and the inadvertent protection of residual tumor cells." (PMID 40723807, 2025). "Notably, recent studies—including our own—indicate that CD47 expression can be induced by AC-CoA, a key metabolic intermediate, and that glycolysis itself may serve as a source of AC-CoA in tumour cells." (PMID 41163221, 2025). "We rationalized that engineering NDV to express an anti-CD47 monoclonal antibody or a SIRPα-Fc immunoadhesin would enable localized delivery of CD47-blocking agents to the tumor microenvironment, thereby enhancing therapeutic specificity while minimizing on-target, off-tumor effects." (PMID 41322194, 2025). "Moreover, numerous preclinical studies have demonstrated the role of STING signaling, particularly in APCs, on tumor antigen cross-presentation and antitumor T cell immunity after various treatments, e.g., chemo/radiation, CD47 blockade, telomerase-targeting agents, and DNA damage." (PMID 38226619, 2024). "Moreover, in cancer, the expression of CD47 was elevated in advanced tumor stages." (PMID 38720108, 2024). "Studies have shown that targeting CD47 with anti-CD47 or a SIRPα fusion protein containing IgG1 Fc could exert dual effects, disrupting CD47-SIRPα interaction and promoting FcγR-mediated phagocytosis, which results in an enhanced clearance of tumor cells by macrophages and other APCs." (PMID 39335665, 2024). "Therefore, inhibition of CD47-SIRPα axis has a significant impact on tumor immunotherapy." (PMID 39318624, 2024). "Moreover, blocking CD47-SIRPα signal showed remarkable anti-tumor effects in preclinical trials." (PMID 38317230, 2024). "Therefore, no comparison could be made between these two groups regarding CD47 staining and pathological tumor stage." (PMID 39795582, 2024). "Furthermore, tumor vascular normalization may also be an important mechanism that increases the efficacy of anti-CD47 Ab treatment of tumors." (PMID 38398223, 2024). "Consequently, IFNGR1 deficiency in MC38 tumor cells did not influence the efficacy of CD47-SIRPα ICB." (PMID 38982116, 2024). "Besides that, binding of anti-CD47 antibodies on tumor cells provides a strong “eat me” signal, which results in more efficient phagocytosis, and thereby it allows better presentation of tumor antigens with subsequent T-cell activation." (PMID 38493445, 2024). "Furthermore, our investigation focuses on examining the correlation between CD47 expression levels and various parameters such as prognosis, the tumor microenvironment (TME), immune escape mechanisms, adaptive immunity, and notably, T-cell exhaustion, within the pan-cancer landscape of TCGA." (PMID 38720108, 2024). "Furthermore, in colorectal cancer, when anti-CD47 and anti-PD-1 combination therapy is administered in addition to radiation therapy (RT), there was a further decrease in tumor volume and increase in percent survival, in both the irradiated and abscopal tumors." (PMID 38261139, 2024). "Therefore, we hypothesize that one of the primary mechanisms through which CD47 regulates tumor immune evasion, tumor progression, and metastasis is through T-cell rejection." (PMID 38720108, 2024). "The extracellular N-terminal IgV domain of CD47 is essential for interacting with the signal regulatory protein α (SIRPα) on the surface of macrophages and dendritic cells, which aids high-CD47-expressing tumor cells and circulating hematopoietic stem cells in avoiding phagocytosis." (PMID 38426113, 2024). "Consequently, we propose that targeting tumor neovascularization could potentially impact the efficacy of anti-CD47 therapy." (PMID 38532108, 2024). "Thus, CD47 expression is upregulated on tumor-infiltrating lymphocytes." (PMID 39652550, 2024).
tumor (continued). "Similarly, CD47 activity increased slowly after laser irradiation and decreased significantly on day 4 postsurgery, as determined by immunofluorescence staining of CD47 in residual tumor tissues." (PMID 39467056, 2024). "Moreover, combining CD47 blockade with other treatments, such as chemotherapy, monoclonal antibodies (e.g., rituximab for B-cell lymphomas), or immune checkpoint inhibitors (e.g., PD-1/PD-L1 inhibitors), can further enhance anti-tumor efficacy." (PMID 39275127, 2024). "However, none of the TCGA tumor datasets showed significant associations between higher CD47 mRNA expression and decreased overall survival using a mean cutoff." (PMID 39201643, 2024). "Besides enhancing phagocytosis via inhibiting the interaction between CD47 and SIRPa, anti-CD47 nanobodies might offer a targeted approach to deliver transgenes to tumor cells expressing CD47." (PMID 38247566, 2024). "Thus, by disrupting with the SIRP-α-CD47 axis (e.g., by using antibodies against SIRPα and CD47), it is possible to restore recognition and phagocytosis of tumor cells by TAMs, and to activate anti-tumor immune responses." (PMID 39065562, 2024). "However, the efficacy of CD47 blockade as a monotherapy for most cancers is limited, suggesting that CD47/SIRPα axis is not the sole mechanism of resistance to macrophage induced phagocytosis of tumor cells." (PMID 38992659, 2024). "Similarly, additional inhibitory proteins upregulated on the tumour cell surface, such as integrin associated protein (CD47), may affect efficacy of phagocytic cells and have been described to promote tumour progression and metastasis in MTC." (PMID 39001359, 2024). "Thus, in addition to blocking interactions with phagocytes, binding of SIRPα-Fc fusion decoys could potentially alter CD47 signaling in tumor cells." (PMID 38495618, 2024). "However, the combination of NextA and anti-CD47 significantly decreased tumor growth, increased immune cell infiltration in the tumor microenvironment (TME), and modulated innate antitumor immunity, especially macrophage and natural killer (NK) cell populations." (PMID 38414061, 2024). "Thus, although the treatment with antibodies against CD47 can induce antitumor immune responses by blocking the inhibitory CD47-SIRPα signaling in tumor cells, it may also potentially promote tumor progression by blocking CD47 signaling in ECs." (PMID 38426109, 2024). "Therefore, enhancing Fcγ receptor binding could be a differentiator for improved engagement of effector cells in tumor tissues compared to all current BsAbs targeting CD47 possessing either IgG1 or IgG4 domains." (PMID 38448430, 2024). "More specifically, exploring the utility of anti-CD47 treatments in conjunction with other tumor-specific opsonizing antibodies, radiation exposure, and immunosuppressive cell-depleting reagents will allow us to determine its full range of efficacy as an anti-tumor response." (PMID 38893093, 2024). "Similarly, CD47 overexpression in the TME allows tumour cells to avoid immune surveillance." (PMID 38468489, 2024). "Additionally, low CD47 expression on tumor-infiltrating CD4+ and CD8+ T lymphocytes may limit immune escape, allowing tumor cells to be more susceptible to T cell attack." (PMID 39652550, 2024). "Therefore, this suggests that targeting both sides of the CD47/SIRPα axis could synergistically control tumor growth by enhancing macrophage-mediated antitumor immunity." (PMID 38414061, 2024). "It is unclear whether these splenic CD8+ T cells are recent emigrants from the tumor or tumor‐draining LN where priming likely occurs, or whether the pro‐inflammatory conditions generated in the spleen upon CD47 × PD‐L1 BisAb treatment may augment the activation of these cells." (PMID 39584189, 2024). "Therefore, CD47 blockade may offer a therapeutic approach for preventing the immune escape of tumor cells." (PMID 38284882, 2024).